ERN1 (endoplasmic reticulum to nucleus signaling 1)
Diseases named in the same sentence as ERN1 in open-access papers (continued):
Sharing a sentence is not in itself a finding about the gene and the disease.
leukemia (15 papers, 2015 to 2026). A malignant (clonal) hematologic disorder, involving hematopoietic stem cells and characterized by the presence of primitive or atypical myeloid or lymphoid cells in the bone marrow and the blood. "The detachment of the chaperone HSPA5 from the luminal portion of the ER integral membrane proteins EIF2AK3, ERN1, and ATF6 is a crucial process in the activation of ER stress in human leukemia and bladder carcinoma cell lines." (PMID 39000233, 2024).
Alzheimer disease (12 papers, 2019 to 2025). A progressive, neurodegenerative disease characterized by loss of function and death of nerve cells in several areas of the brain leading to loss of cognitive function such as memory and language. "The ERN1 association identified from the TRAPD burden test also mimics an exome-wide association study of APOE ε4 non-carrier Alzheimer’s disease which found a rare synonymous variant in ERN1 (rs56201815) as being associated with late-onset Alzheimer’s disease (LOAD)." (PMID 36175824, 2022). "Consistently, Ern1 was highly expressed in Alzheimer’s disease induced by neurotoxicity, where inhibiting Ern1 was found beneficial for treatment." (PMID 32272965, 2020).
cervical cancer (11 papers, 2017 to 2024). A primary or metastatic malignant neoplasm involving the cervix. "APMAP promotes the EMT and metastasis of cervical cancer cells by activating the Wnt/β-catenin pathway, and ERN1 is related to the apoptosis of cervical cancer cells." (PMID 37689639, 2023). "Six interesting core DEPs (SPARC, HPX, VCAM1, TFRC, ERN1 and APMAP) were confirmed to be potential plasma diagnostic markers for LVSI and LNM in cervical cancer patients." (PMID 37689639, 2023).
ischemic stroke (8 papers, 2015 to 2025). A stroke disorder caused by obstruction of blood flow to the brain, due to thrombotic (local blood clot formation) or embolic (due to a blood clot or other material traveling from another site) event. "However, some studies have also identified that ERN1 signalling also exerts a neuroprotective response which supports that the ERN1-pathway may be pro-survival in ischaemic stroke through the activation of chaperone proteins." (PMID 36175824, 2022).
Stroke (8 papers, 2017 to 2024). Sudden impairment of blood flow to a part of the brain due to occlusion or rupture of an artery to the brain. "The ER stress response has been well studied to aggravate the loss of neuronal function in stroke, in which ERN1 plays a vital signal role." (PMID 37305740, 2023).
Arthritis (7 papers, 2017 to 2024). Inflammation of a joint. "Specific deficiency of ERN1 in chondrocytes spontaneously resulted in OA-like cartilage destruction and accelerated OA progression in a surgically induced arthritis model." (PMID 37907740, 2023). "The study found that cartilage-specific deficiency of ERN1 in mice led to spontaneous osteoarthritis development and more severe cartilage damage in a surgically induced arthritis model." (PMID 37907740, 2023). "In the ERN1 cKO ACLT mouse model, more severe loss of proteoglycan in safranin O staining, a significantly higher arthritis score, elevated expression of MMP13 and ADAMTS5, and reduced expression of aggrecan and Col2 were observed." (PMID 37907740, 2023).
Cognitive impairment (7 papers, 2021 to 2025). Abnormal cognition is characterized by deficits in thinking, reasoning, or remembering. "Deactivation of the RNase domain of ERN1 in neurons reduces all hallmarks of AD including amyloid-beta load, cognitive impairment, and astrogliosis in 5xFAD mice." (PMID 33637690, 2021).
bladder cancer (6 papers, 2015 to 2025). "We also discovered that ER stress component, like HSPA5, ERN1, ATF4 and DDIT3, increased when the human bladder cancer cells were treated with BIX-01294." (PMID 25685062, 2015).
injury (6 papers, 2020 to 2023). Damage inflicted on the body as the direct or indirect result of an external force, with or without disruption of structural continuity. "Thus, we speculated that silencing Ern1 expression may attenuate nerve injury in SCIRI." (PMID 32272965, 2020).
osteoarthritis (6 papers, 2021 to 2025). A noninflammatory degenerative joint disease occurring chiefly in older persons, characterized by degeneration of the articular cartilage, hypertrophy of bone at the margins and changes in the synovial membrane. "This study provides new insights into OA pathogenesis and the UPR and suggests that IRE1α/ERN1 may serve as a potential target for the treatment of joint degenerative diseases, including OA." (PMID 37907740, 2023). "Given the uncertainties in the regulation of cartilage function by IRE1α and the remarkable complexity and heterogeneity exhibited by osteoarthritis, it is important to elaborate on the mechanism of ERN1/IRE1α in the occurrence and development of osteoarthritis." (PMID 37907740, 2023).
Burkitt lymphoma (4 papers, 2010 to 2022). A rare form of malignant mature B-cell non-Hodgkin lymphoma. "Along these lines, another study in Burkitt's lymphoma cells reports that c‐Myc binds the E‐box sequences in the promoters of both ERN1 and XBP1 genes, establishing c‐Myc as a direct upstream regulator of the IRE1α‐XBP1s pathway." (PMID 32310340, 2020).
non-alcoholic fatty liver disease (4 papers, 2018 to 2025). "Molecular docking coupled with molecular dynamics simulations was employed to evaluate the binding patterns and dynamic stability of Resmetirom—a drug approved for the treatment of nonalcoholic fatty liver disease in adults—with the protein structures of ERN1 and SLC11A1." (PMID 41378206, 2025).
brucellosis (2 papers, 2016 to 2022). Brucellosis is a bacterial infection that spreads from animals to people via unpasteurized dairy products or by exposure to contaminated animal products or infected animals. "To extend these findings to an in vivo model of brucellosis, we tested the hypothesis that UPR and IRE1α confer susceptibility to Brucella infection in mice harboring a conditional mutation in Ern1, the gene encoding IRE1α." (PMID 35587649, 2022).
dental caries (2 papers, 2020 to 2022). The decay of a tooth, in which it becomes softened, discolored, and/or porous. "We found that genetic variation in ERN1 (rs196929), an ER stress variant, was associated with dental caries and periodontal disease." (PMID 36167768, 2022).
vasculitis (2 papers, 2022 to 2024). "To further assess the role of the IRE1 pathway in myeloid cells in the LCWE murine model of KD vasculitis, we generated LysΜCre+Ern1Δ/Δ mice, in which myeloid cells are IRE1 deficient." (PMID 35167493, 2022).
breast tumor (1 paper, 2019). "It was reported that knocking down either ERN1 or ALPK1 could push bipotential breast tumor-initiating cells towards the luminal fate." (PMID 31636652, 2019).
gram-negative bacterial infections (1 paper, 2016). Infections caused by bacteria that show up as pink (negative) when treated by the gram-staining method. "Upon Gram-negative bacterial infection, diptericin expression was increased by >2,000-fold over the non-infected control, which was significantly reduced in RPN5 and ERN1 RNAi lines." (PMID 27819340, 2016). "In addition, ERN1 RNAi fly also showed a substantial increase in the diptericin expression in the non-infected condition which also increased by Gram-negative bacterial infection." (PMID 27819340, 2016). "Therefore, we tested whether RPN5, ERN1 and Bap60 can also regulate IMD-mediated NF-κB activation as measured by diptericin expression in response to Gram-negative bacterial infection using the constitutive RNAi expression system." (PMID 27819340, 2016). "Next, we tested whether inducible knockdown of RPN5, ERN1, and Bap60 can also regulate Toll- and IMD-mediated NF-κB activation by measuring drosomycin and diptericin expression, respectively, in Gram-positive and Gram-negative bacterial infection conditions in the C654ts-Gal4 RNAi flies." (PMID 27819340, 2016).
gram-positive bacterial infections (1 paper, 2016). Infections caused by bacteria that retain the crystal violet stain (positive) when treated by the gram-staining method. "The qPCR results using the constitutive RNAi expression system (C564-GAL flies) showed that drosomycin expression was increased by >10-fold by Gram-positive bacterial infection in the control RNAi flies, which was significantly reduced in RPN5 and ERN1 RNAi lines." (PMID 27819340, 2016).
osteonecrosis of (1 paper, 2023). "The Venn diagrams showed six intersecting genes related to osteonecrosis of the femoral head, OS and APO targets: NFE2L2 (Nrf2), ERN1, PDGFRB, PDGFRA, KEAP1 and CDK1." (PMID 37749949, 2023).
pancreatic ductal adenocarcinoma (1 paper, 2020). An infiltrating adenocarcinoma that arises from the epithelial cells of the pancreas. "In the mesenchymal pancreatic ductal adenocarcinoma mouse models with activated c‐Myc, constitutive knockdown of Ern1 potently impairs 3D clonogenic cell growth and suppresses tumorigenicity in orthotopic transplants in vivo." (PMID 32310340, 2020).
periodontal disease (1 paper, 2022). "However, this pre-selection of patients with tooth loss might eliminate the oral health confounders of associations between cancer and genetic variation in ERN1 such as our previously detected correlations with periodontal disease and periapical lesions." (PMID 36167768, 2022).
reproductive system cancer (1 paper, 2022). "In the logistic regression, when we stratified the analysis by each type of cancer and adjusted by age, sex, ethnicity and smoking habits we found associations between the rs196929 in ERN1 and skin, breast and male’s reproductive system cancers (p < 0.05)." (PMID 36167768, 2022). "We found a nominal association between this same ERN1 marker and male’s reproductive system cancer, but this association should be interpreted with caution since there is a possibility that it is due to chance." (PMID 36167768, 2022).
skin cancer (1 paper, 2022). "To date, very few studies have focused on the role of the ER stress pathway genes and skin cancer and, to the best of our knowledge, this is the first time that the rs196929 ERN1 marker was associated with cancers." (PMID 36167768, 2022).
ulcers (1 paper, 2023). "This, accompanied by the high abundance of amyloid-beta precursor protein (APP), apolipoprotein E (APOE), MADD (MAP kinase-activating death domain protein), ATF6B, ERN1 and TRAP1 in the presence of ulcers, shows that, along with cell death, the epithelial health maintenance response is strong." (PMID 37170213, 2023).
tumor (296 papers, 2010 to 2026). "Other genes that are associated with poor prognosis and tumor progression, such as ODC1, ERN1, and ETS2, were also downregulated primarily in the samples treated with Se-E2, Se-K2 and Se-C3." (PMID 36839934, 2023). "In order to test which intracellular factors reflect the oncolysis ability of OVM cooperating with the receptor MXRA8, we compared the oncolytic ability of OVM with the ZAP, ERN1 or RHOQ expression in several tumor cells using Spearman’s correlation." (PMID 35393389, 2022). "We analyzed the gene expression data from the normal and tumor groups in different databases, and it was revealed that 7 genes were significantly different except for ERN1." (PMID 35614390, 2022). "The tumor promoting role of ERN1 is consistent with previous reports that IRE1α activity correlates in a cause-effect relationship with GBM aggressiveness." (PMID 32433555, 2020). "Based on survival data, we isolated F4/80 tumor-infiltrating macrophages of tumor-bearing Ern1-CKO mice to assess the UPR/IIS and Cd274 gene expression status." (PMID 32520957, 2020). "A strong selection against the continued suppression of ERN1 or ALKP1 occurs during tumor development in vivo over time." (PMID 27829216, 2016). "At the same time, in the RLS40 model, DNase treatment resulted in a decrease in the mRNA levels of pro-tumor phenotype markers (Ccl17, Il10) and an increase in the mRNA levels of anti-tumor phenotype markers (Icam1, Tnfa, Vegfr1), as well as cell mobilization genes (Ern1, Stat3)." (PMID 40867260, 2025). "Notably, tumor-infiltrating macrophages in tumor-bearing Ern1 (-/-) mice had a marked reduction in spliced Xbp1, Il-23p19, Arg1 and Cd274 gene expression compared to their Ern1 fl/fl counterpart." (PMID 35237269, 2022). "The UPR and autophagy are also interconnected via ERN1 in tumor cells." (PMID 36497321, 2022). "On the other hand, the lack of a positive correlation with ERN1 motivated further analysis given that this pathway has been implicated in tumor survival, macrophage polarization, and T‐cell dysregulation." (PMID 34698427, 2021). "ERN1 was downregulated in shFOXK2-transduced OVCAR5 and OVCAR3 cells and human HGSOC tumor cells compared with control cells and tumors." (PMID 35349489, 2022). "Under ER stress many proteins including HSPA5, HSP90B1/GRP94, ER-associated degradation, PDI (protein disulfide isomerase), ATF6, ERN1, XBP1, EIF2AK3 and EIF2A are overexpressed in many forms of tumor cells." (PMID 36497321, 2022). "ERN1 is a transmembrane serine/threonine protein kinase for endoplasmic reticulum hemostasis, and its downstream target XBP1 is activated for tumor growth." (PMID 36139553, 2022). "We also integrated the macrophage score with ERN1 and EIF2AK3 to predict CD274 expression in an ordinary least squares (OLS) linear regression model, including the tumor type as a covariate." (PMID 32520957, 2020). "This was also shown by the total UPR expression profile and post cell-treatment with GSK2606414, which revealed the suppression of major UPR driver genes, including IRE1 (ERN1) and XBP1, which are key players in MM tumor growth." (PMID 33028016, 2020). "Ern1- or Xbp1-CKO macrophages enabled us to distinguish different roles within the IRE1α/XBP1 axis relative to immune dysregulation and tumor growth." (PMID 32520957, 2020). "We found a strong re-expression of ERN1 and ALPK1 in the tumor cells arising from an ERN1 knockdown after late tumor passage." (PMID 27829216, 2016). "We present evidence for a role of ERN1 (endoplasmic reticulum to nucleus signaling 1), also known as IRE1 alpha (inositol-requiring 1), and ALPK1 (alpha-kinase 1) in inhibiting the spontaneous differentiation of mammary bi-lineage tumor-initiating cells." (PMID 27829216, 2016).
tumor (continued). "We utilized qRT-PCR to validate increased expression of various transcripts related to the IRE1α/XBP1 arm of the UPR, such as IRE1 (gene name: Ern1), Xbp1, Dnajb9, Edem1, and CHOP (gene name: Ddit3) in GA muscle of KPC tumor-bearing mice compared to control mice." (PMID 40655023, 2025). "Moreover, MAPK/JNK activation through the ERN1-MAPK/JNK-BECN1 complex initiates autophagy and helps tumor cells to adapt to UPR conditions." (PMID 36497321, 2022). "We observed genetic heterogeneity also in spheroids for several genes, as indicated by low SNV frequencies, for instance, in ADAMTS7, CSMD3, ERN1, FAT3, and RAD51C/D, supporting the view that tumor lesions are composed of mixed tumor cell populations with varying frequencies of SNVs." (PMID 32533757, 2020). "B16.F10 tumor–bearing mice with conditional Ern1-KO but not Xbp1-KO macrophages had significantly greater survival than their fl/fl controls." (PMID 32520957, 2020). "Similarly, although the difference was not as great, tumor tissues had higher levels of IRE1α (ERN1) expression." (PMID 41350724, 2025). "Besides Pmp22, it is highly possible that other RUNX1/3 targets, such as SDC4, ERN1, and/or MBP, might be involved in tumor formation." (PMID 31032403, 2019). "However, vorinostat did not increase CTL lysis of tumor cells when ERN1 or PERK were silenced." (PMID 26862729, 2016).
cancer (282 papers, 2010 to 2026). A tumor composed of atypical neoplastic, often pleomorphic cells that invade other tissues. "Our results show a statistically significant association between the rs196929 in ERN1, and all types of cancer combined in the genotypic (2 degrees of freedom) model (p = 0.0058)." (PMID 36167768, 2022). "Our results showed a statistically significant association between the rs196929 in ERN1, and cancer overall in both the additive and dominant models (OR = 1.37, 95% C.I. 1.06–1.79, p = 0.014)." (PMID 36167768, 2022). "An additional nominal association between the rs196929 in ERN1 and male’s reproductive system cancers (OR = 1.96, 95% C.I. 1.07–3.59, p = 0.028) was identified." (PMID 36167768, 2022). "In fact, ERN1, the gene coding for IRE1, was found to rank fifth among all the genes coding for human protein kinases carrying driver mutations across various human cancers." (PMID 31071975, 2019). "Development of next generation EIF2AK3 inhibitors or ERN1 inhibitors may yield selective agents which can directly modulate the UPR in cancer-associated bone disease." (PMID 40877255, 2025). "With the hypothesis that the family history of cancer drove our previous results, this current study aims to test if ERN1 rs196929 variant is overrepresented in individuals with a diagnosis of cancer using a cohort of patients going for regular dental treatment." (PMID 36167768, 2022). "We hope that our study helps inform future genetic and epidemiologic studies on cancers and the rs196929 ERN1 marker, as well as helps drive attention to the potential for oral health indicators of general health outcomes such as cancers." (PMID 36167768, 2022). "A later study from our group showed an excess of the less common homozygote of ERN1 rs196929 among relatives of individuals born with cleft lip and palate when they had positive family history of cancer." (PMID 36167768, 2022). "In the cancer-cells, transfection efficiency was determined via qPCR and showed a 40% reduction in the ERN1-mRNA-expression in HepG2-cells and 65% in the Huh7-cells." (PMID 33103995, 2020). "We challenged multiple cancer cell lines with ERN1 or ALPK1 siRNA and assessed proliferation and colony forming ability from single cells." (PMID 27829216, 2016). "The 3D colony formation assay which is widely used to assess cancer stem cell self-renewal in vitro was more sensitive to the suppression of ERN1 and ALPK1 than the 2D assay." (PMID 27829216, 2016). "Cancer induced hepatic expression of ER-stress markers BiP (binding immunoglobulin protein), IRE-1α (endoplasmic reticulum to nucleus signaling 1), and inflammatory intermediate STAT-3 (signal transducer and activator of transcription 3)." (PMID 25789991, 2015). "The IRE1 protein is encoded by the ERN1 gene and knockdown of this gene in hypoxic U87 GBM cells shows complex regulation of many downstream targets important for cancer cell survival and proliferation." (PMID 37107600, 2023). "Moreover, IRAK2 downregulation compromised ERN1 signalling and autophagy, which are pathways that are frequently exploited by cancer cells to survive, further supporting the beneficial impact of IRAK2 downregulation in TNBC." (PMID 36768848, 2023). "ERN1 expression was also significantly increased in FOXK2-OE OC (OVCAR5 and OVCAR3) and non-cancer (FT190 and NoEM) cells." (PMID 35349489, 2022). "UPR effectors, including ERN1 (IRE1α), ATF6, and PERK (EIF2AK3), dissociate from HSPA5 (GRP78) and activate their respective canonical targets (XBP1s, ATF6α, and ATF4); subsequently trigger transcriptional reprogramming that promotes the survival of cancer cells under ER stress." (PMID 40821803, 2025).